LRRK2 (leucine rich repeat kinase 2)
Diseases named in the same sentence as LRRK2 in open-access papers (continued):
Sharing a sentence is not in itself a finding about the gene and the disease.
Parkinson disease (continued). "This mutation enhances in vitro protein kinase activity ∼3-fold, indicating that abnormal increase in the kinase activity of LRRK2 is involved in the pathogenesis of Parkinson's disease, suggesting that LRRK2 kinase inhibitors have therapeutic benefit for the treatment of Parkinson's disease." (PMID 27474410, 2016). "This phenotype is interesting, given the increased incidence of cognitive impairment reported in both sporadic and LRRK2 Parkinson's patients, although other studies suggest that certain forms of cognitive dysfunction may be less prevalent in LRRK2 carriers." (PMID 26744332, 2016). "Finally, another protein kinase mutated in Parkinson's disease termed PINK1, indirectly controls the phosphorylation of a small group of Rabs including Rab8A at a site distinct from that used by LRRK2 (Ser111 on Rab8A)." (PMID 27474410, 2016). "Immunohistochemical study of Lewy bodies identified both WSB1 and LRRK2 within Lewy bodies associated with LRRK2-associated Parkinson’s Disease, but not PD associated with a different etiology." (PMID 27542736, 2016). "In our study we detected no alteration in the adhesion of fibroblasts from Parkinson patients carrying LRRK2 mutations in the kinase domain or in the ROC domain compared to fibroblasts from healthy controls carrying wild type LRRK2." (PMID 25830304, 2015). "EDS and RBD were always reported to start after the onset of parkinsonism in LRRK2-PD." (PMID 26177462, 2015). "Nonmotor symptoms in patients with LRRK2 G2019S associated Parkinson’s disease, idiopathic Parkinson’s disease and healthy subjects." (PMID 25330404, 2014). "Lewy bodies (LB) is the most typical and widely spread pathology in LRRK2 parkinsonism which restricted to the brainstem, the cortex and limbic system, or in the case of pure nigral degeneration may be absent altogether." (PMID 25391693, 2014). "Silencing ArfGAP1 expression was shown to protect against mutant LRRK2 induced neurite shortening, suggesting that ArfGAP1 might also be a potential target in the Parkinson’s disease." (PMID 24926233, 2014). "However, recent report has identified one patient with LBD and one patient with glial cytoplasmic inclusions (GCIs) whcich highlights the pleomorphic pathology in LRRK2 parkinsonism." (PMID 25391693, 2014). "Despite intense research efforts in the context of Parkinson's disease (PD), the basic neurophysiology of LRRK2 remains largely unknown." (PMID 25309331, 2014). "Nevertheless, genetically defined cohorts of patients with parkinsonism such as LRRK2 p.G2019S parkinsonism might allow the identification of biomarkers of disease progression and inform clinical trials." (PMID 25061481, 2014). "Research into the function of these domains exploded with their identification in a number of proteins linked to human disease, including leucine-rich repeat kinase 2 (LRRK2) and death-associated protein kinase 1 (DAPK1) in Parkinson’s disease and cancer, respectively." (PMID 24981771, 2014). "Of course, markers that may reflect these processes in LRRK2 Parkinson disease may also be applicable to non-LRRK2 Parkinson disease." (PMID 23823465, 2013). "In addition, many of the studies have focused on miRNA targets related to already known disease genes, such as LRRK2 in Parkinson's disease and BACE1 in Alzheimer's disease." (PMID 24133413, 2013). "Studies are currently underway to determine whether there are specific biochemical or imaging profiles that reflect disease expression and progression in both LRRK2 Parkinson disease patients and asymptomatic carriers." (PMID 23823465, 2013). "Mutations in leucine-rich repeat kinase 2 (LRRK2) underlie an autosomal-dominant form of Parkinson's disease (PD) that is clinically indistinguishable from idiopathic PD." (PMID 23646112, 2013).
Parkinson disease (continued). "Further investigation in Parkinson's disease cases revealed a significant decrease of miR-205 in the frontal cortex compared to controls and in vitro luciferase assays confirmed a direct interaction of this miRNA with LRRK2 mRNA." (PMID 24133413, 2013). "Although mutations in LRRK2 are known to confer risk of developing CD and also Parkinson’s disease, little evidence for its pathological function exists." (PMID 24137160, 2013). "This novel regulatory mechanism for LRRK2 suggests miR-205 may serve as a therapeutic target for Parkinson's disease." (PMID 24133413, 2013). "Genetic evidence links mutations in the LRRK2 gene with an increased risk of Parkinson’s disease, for which no neuroprotective or neurorestorative therapies currently exist." (PMID 23799078, 2013). "In the LRRK2 pathway, for example there was no LRRK2, a protein associated with Parkinson’s disease." (PMID 24312404, 2013). "LRRK2 is one of the most important genetic contributors to Parkinson’s disease (PD)." (PMID 24211199, 2013). "In addition, connections between LRRK2 and Wnt cascades are strengthened by a number of studies supporting a role for dysregulated Wnt signaling in the early stage of Parkinson’s disease." (PMID 23754980, 2013). "The characterization of LRRK2 knockout rats may prove to be extremely valuable in understanding potential safety liabilities of LRRK2 kinase inhibitor therapeutics for treating Parkinson’s disease." (PMID 24244710, 2013). "In particular for monogenic forms of disease, patient-derived iPSCs have already been shown to recapitulate known disease mechanisms, as shown in spinal muscular atrophy, fragile X syndrome, progeria syndrome, and several genetic forms of Parkinson disease (PD) like LRRK2, PINK1, SNCA, and GBA." (PMID 22567022, 2012). "Parkinson’s disease is perhaps the outlier, because α-synuclein and Lewy bodies have not yet been associated with SG biology, but leucine rich repeat kinase 2 (LRRK2) is known to modulate RNA translation, which points to a link with SG biology." (PMID 23164372, 2012). "This indicates that inhibitors of LRRK2 activity might be of therapeutic benefit for the treatment of Parkinson’s disease." (PMID 22723946, 2012). "A fourth Parkinsons gene, LRRK-2, is a protein kinase that, unlike Pink, Parkin and DJ-1, (which are recessive alleles resulting in Parkinsons Disease) acts as a dominant mutation responding to ROS by initiating programmed cell death." (PMID 23211569, 2012). "In fact, when variants with particularly large effects do exist—such as APOE in Alzheimer’s disease, BRCA1 and BRCA2 in breast and ovarian cancer, and LRRK2 in Parkinson’s disease —previous authors have suggested simulations in lieu of their analytical approximation." (PMID 22827772, 2012). "Although tau pathology was not investigated in these other models, staining for the Parkinson’s disease associated proteins α-synuclein and leucine rich repeat kinase-2 (LRRK2) was reported in Atg7-deficient DA neurons." (PMID 22998728, 2012). "Mutations in the leucine-rich repeat kinase 2 gene cause late-onset Parkinson's disease with a clinical appearance indistinguishable from Parkinson's disease idiopathic." (PMID 22970411, 2012). "Genetic linkage studies of Parkinson's Disease (PD) have identified susceptibility loci in five genes which include SNCA (PARK1), Parkin (PARK2), PTEN-induced putative kinase (PINK1;PARK6), DJ-1 (PARK7) and Leucine rich repeat kinase 2 (LRRK2; PARK8)." (PMID 21812969, 2011). "In this study, we have investigated whether ASP-RNAi may be a feasible approach for the treatment of LRRK2-based Parkinson's disease." (PMID 21712955, 2011).
Parkinson disease (continued). "The expression pattern of LRRK2 protein and its possible role in immune cell maturation raise the question as to whether LRRK2 constitutes a link between the immune system and Parkinson's disease." (PMID 21738687, 2011). "The main goal of this work was to describe two MJD patients displaying the parkinsonian triad (tremor, bradykinesia and rigidity), namely on what concerns genetic variation in Parkinson's disease (PD) associated loci (PARK2, LRRK2, PINK1, DJ-1, SNCA, MAPT, APOE, and mtDNA tRNAGln T4336C)." (PMID 22023810, 2011). "Finally, it will be vital to work out how 14-3-3 affects LRRK2 function andwhether this is relevant to understanding the role of LRRK2 in Parkinson's disease." (PMID 20659021, 2010). "Similarly, the European and Asian LRRK2 disease-causing mutational spectrum, including LRRK2 p.Gly2019Ser and p.Gly2385Arg genetic risk factors, did not appear to play a major role in Parkinson's disease aetiology among West African ancestry populations." (PMID 41058593, 2026). "The combination of non-rodent genetics and molecular biology may significantly contribute to the understanding of the role of LRRK2 in Parkinson’s disease and pave the way for new therapeutic possibilities, including compounds capable of reducing neuroinflammation." (PMID 40076730, 2025). "Furthermore, through molecular docking and mouse model studies, we have unraveled the interactions between LRRK2 and the p62-Keap1-Nrf2 pathway, laying a solid foundation for understanding the pathological mechanisms of Parkinson’s disease and developing targeted therapeutic strategies for LRRK2." (PMID 40169487, 2025). "By establishing a site and machinery for LRRK2 activation, these results provide a new avenue for investigating the regulation of LRRK2 activity in the context of normal physiology as well as human diseases such as Parkinson’s disease, Crohn’s disease, and microbial pathogenesis." (PMID 39812709, 2025). "Therefore, research on LRRK2 and GBA1 may be essential to understand the biology underlying neuronal degeneration in Parkinson's disease." (PMID 40397198, 2025). "In addition to PARK6 (encoding PINK1) and PARK2 (encoding Parkin), other genes associated with Parkinson’s disease, such as PARK7 (encoding the DJ-1 protein) and PARK8 (encoding the LRRK2 protein), are also thought to be mutated in patients with Parkinson’s disease." (PMID 40463912, 2025). "Human pegivirus (HPgV), for example, is generally regarded as harmless; however, its capacity to modulate immune pathways—and to interact with host genetics such as LRRK2—suggests it could still influence neuroinflammation, mitophagy, and disease progression in Parkinson’s disease." (PMID 41199954, 2025). "Given the limited scope of biomarker assessments available at the time of analysis, this study provides limited insight into potential pathogenic mechanisms that may or may not diverge in LRRK2 parkinsonism CSFasynSAA− versus SAA+ cases." (PMID 40114783, 2025). "Along these lines, neuronal disposal of protein aggregates and mitochondria via shedding from neurons for clearance by neighboring glial cells has been observed in other contexts but has not yet been linked to LRRK2 or its aberrant activity in Parkinson’s disease." (PMID 40758897, 2025). "Mutations in these genes cause lysosomal swelling and fragmentation, phenotypes that resemble those known to activate LRRK2, suggesting that LRRK2 may be engaged by lysosomal stresses across a broader context of Parkinson’s disease-relevant genetic perturbations." (PMID 41332754, 2025). "Although mutations that increase LRRK2 kinase activity are only found in a subset of Parkinson’s disease patients, the strong link between LRRK2 kinase activity and Parkinson’s disease suggests that other factors that modulate LRRK2 kinase activity could have disease-relevant consequences." (PMID 39812709, 2025).
Parkinson disease (continued). "Individuals with Parkinson’s disease who carry distinct gene variants, such as LRRK2 risk variants (G2385R, and/or R1628P, and/or S1647T), SNCA rs1045722/T, Parkin-related mutations, GBA, or LRRK2 G2019S mutation, have presented a diverse spectrum of disease progression patterns." (PMID 40308892, 2025). "Indeed, three well validated autosomal dominant genes (SNCA, LRRK2, and VPS35) and three well validated autosomal recessive genes PRKN, PINK1, and DJ1 are known to cause Parkinson’s disease, inducing defects in mitochondria, axonal transport, and the dopaminergic system." (PMID 41302176, 2025). "Additionally, 3-5% of cases can be attributed to monogenic inheritance associated with known Parkinson's disease-related genes, such as SNCA, LRRK2, VPS35, PRKN, PINK1, DJ-1, and GBA, while genetic variants collectively account for 16-36% of the non-monogenic heritable risk." (PMID 38879763, 2024). "In addition to pathogenic mutations in well-established PD-related genes (LRRK2, PRKN, PINK1, SNCA, PLA2G6 and GBA1), we identified pathogenic mutations in genes that have been reported to present as levodopa-responsive parkinsonism but typically present with alternative or atypical phenotypes." (PMID 39420034, 2024). "Furthermore, many genetic forms of parkinsonism are not invariably associated with LP, such as LRRK2- and PRKN-PD." (PMID 38391726, 2024). "Two laboratories failed to report the pathogenic LRRK2 variant in the patient with Parkinson’s disease - in one of the two cases this was because the gene panel investigated did not contain the LRRK2 gene, which is a major gene linked to the referral request of testing for Parkinson ́s disease." (PMID 38839988, 2024). "Indeed, findings have emerged from PPMI4 demonstrating that among individuals with LRRK2-associated parkinsonism, absence of detectable asyn aggregates is most prevalent among those who are normosmic, especially among females." (PMID 39108519, 2024). "Despite the effects directly obtained in OPCs in vitro, LRRK2 inhibition with compound 4 may reflect the anti‐inflammatory effect that is previously known from different scenarios and very recently suggested in patients with Parkinson's disease, too." (PMID 38287523, 2024). "Genetic variants in GBA1 and LRRK2 genes are the commonest genetic risk factor for Parkinson disease (PD); however, the preclinical profile of GBA1 and LRRK2 variant carriers who will develop PD is unclear." (PMID 36881256, 2023). "Likewise, in another fly model of Parkinson’s disease caused by the mutation in leucine-rich repeat kinase 2 (LRRK2), the most common genetic cause of both familial and sporadic Parkinson’s disease, global protein translation rate was elevated due to phosphorylation of ribosomal protein s15." (PMID 36711035, 2023). "Therefore, we aim to address the role of LRRK2 inhibitors in parkinsonism models without LRRK2 mutations." (PMID 38020716, 2023). "While the functional role of Pppm1h remains uncertain, researchers recently reported that Ppm1h can counteract LRRK2 signaling via Rab protein dephosphorylation, which may potentially link to the molecular mechanisms of LRRK2-mediated neurological disorders such as Parkinson’s disease." (PMID 37806341, 2023). "Both forms of Parkinson disease (PD) involve profound dopaminergic neuronal degeneration and gliosis in the SNpc, decreased dopamine levels in the caudate putamen, and Lewy body pathology in the brainstem; therefore, understanding LRRK2 plays an essential role for all forms of PD." (PMID 37445986, 2023). "However, it is known that the mutated LRRK2 does not necessarily lead to PD onset, and many individuals live with this mutation without developing Parkinson’s disease." (PMID 37165152, 2023). "Furthermore, a Parkinson's causing mutation in VPS35[D620N] stimulates LRRK2 activity without impacting LRRK1." (PMID 36040231, 2022).
Parkinson disease (continued). "Additionally, TPC2 can associate with the leucine-rich repeat kinase 2 (LRRK2), mutations in which are linked to late-onset Parkinson’s disease, and the mammalian target of rapamycin (mTOR), a serine/threonine protein kinase that when hyperactivated leads to increased growth and proliferation." (PMID 36046356, 2022). "More than 30 loci are identified as risk factors for PD, some of which are extensively studied, such as mutations in genes encoding synuclein (SNCA), leucine-rich repeat kinase 2 (LRRK2), parkin (PRKN), and Parkinson disease protein 7 (PARK7)." (PMID 35805174, 2022). "Interestingly, our results identified several loci that have been previously associated with the risk of Parkinson’s disease (e.g.: LRRK2, ITKB, CCDC62), but no loci overlapping with frontotemporal dementia in addition to the MAPT locus." (PMID 35589863, 2022). "Notably, these numbers are quite different in LRRK2 parkinsonism cases." (PMID 33494262, 2021). "What are the associations of concurrent LRRK2 G2019S and GBA variations with clinical progression of Parkinson disease (PD)?" (PMID 33881531, 2021). "The main genes related to PD are α-synuclein, leucine-rich repeat kinase 2 (LRRK2) and protein deglycase (DJ-1, also known as Parkinson disease protein 7)." (PMID 34948191, 2021). "Furthermore, the estimate prevalence of LRRK2‐related Parkinson's disease (PD; OMIM# 607060) among non‐Ashkenazi Jewish carriers of the monoallelic variant NM_198578.4:c.6055G>A (p.Gly2019Ser) was found to be 7.33% at 60 years, 29.17% at 70 years, and 42.52% at 80 years." (PMID 33816657, 2021). "To see if a similar phenomenon exists also for C9orf72 intermediate repeats, we analyzed Parkinson’s disease patients of Ashkenazi origin, in a stratified manner, in carriers of mutations in LRRK2, GBA, and/or SMPD1 genes, and in patients that do not carry these mutations." (PMID 34440384, 2021). "The fact that we could rescue G2019S-impared mitophagy in PD-relevant cell types, within the brain, provides an exciting prospect that LRRK2 inhibitor-mediated correction of mitophagic defects in Parkinson’s patients could have therapeutic utility in the clinic." (PMID 34340748, 2021). "Finally, 21–54% of LRRK2-associated Parkinson’s disease patients do not show apparent Lewy bodies in the SN although they show loss of dopaminergic neurons in this area." (PMID 32269512, 2020). "However, some mutations, such as LRRK2, are also present at a significant rate in non-familial late-onset Parkinson’s disease patients." (PMID 31324919, 2019). "Systematic review and meta-analysis in which a PubMed search of interventional and noninterventional studies of Parkinson disease with LRRK2, GBA, or PRKN gene mutations published between January 1, 1990, and May 1, 2018, was conducted." (PMID 30707228, 2019). "We show clearly that LRRK2 mutations are present at a significant rate in patients with onset under 50 years (2.2%), and that SNCA mutations are present in 1.5% of patients with a strong family history of Parkinson’s disease (two or more additional family members affected)." (PMID 31324919, 2019). "Additionally, Ca2+ signals evoked by NAADP were enhanced in LRRK2- in Parkinson's." (PMID 29746898, 2018). "Indeed, elevated levels of LRRK2 have been reported in patients with Parkinson disease." (PMID 30571694, 2018). "In addition, there are common protein-coding and non-protein-coding variants at the LRRK2 locus that moderately increase the risk for developing Parkinson's." (PMID 29127255, 2018). "Further, compared to LRRK2 WT the disease variants G2019S and R1441C exhibits increased pThr73 levels in HEK293 cells thereby confirming literature reports that LRRK2 exonic variation associated with Parkinson’s disease impacts the level of Rab10 phosphorylation." (PMID 28860483, 2017).